MIR378A (microRNA 378a)
Synonyms: hsa-mir-378; MIR378; MIRN378; hsa-mir-378a; miRNA378
Gene: MicroRNA gene on chromosome 5 (149,732,825 to 149,732,890, forward strand). Ensembl gene ENSG00000199047.
Gene Ontology:
Biological process: miRNA-mediated post-transcriptional gene silencing
Homologues: Orthologues: chimpanzee ptr-mir-378a (100% identical), macaque MIR378A (98% identical), mouse Mir378a (98% identical), rabbit MIR378A (98% identical), guinea pig MIR378A (97% identical), pig ssc-mir-378-1 (97% identical). Paralogues in human: MIR378B (52% identical), MIR378D2 (47% identical).
Diseases named in the same sentence as MIR378A in open-access papers:
MIR378A is named in the same sentence as 3 diseases in open-access papers, as found by Europe PMC text mining. Sharing a sentence is not in itself a finding about the gene and the disease.
MIR378A shares sentences with these, for which no sentence is quoted: Glucose intolerance (1 paper); metabolic syndrome (1); Obesity (1).